MIR4644 (microRNA 4644)
Synonyms: hsa-mir-4644
Gene: MicroRNA gene on chromosome 6 (170,330,761 to 170,330,844, forward strand). Ensembl gene ENSG00000266245.
Homologues: Orthologues: chimpanzee MIR4644 (100% identical).